IL4 (interleukin 4)
Diseases named in the same sentence as IL4 in open-access papers (continued):
Sharing a sentence is not in itself a finding about the gene and the disease.
cancer (continued). "The N1 phenotype with high levels of TNF-α, IL-2, IL-4, IL-7, and IL-10 expression induces a cytotoxic effect to cancer cells and hampers cancer cell progression." (PMID 35267547, 2022). "If we use IL-2, IL-4, and IL-12 as the adjuvant in cancer vaccine therapy, we need them to activate effector T cells." (PMID 35967400, 2022). "Genetic variants of IL-4 and CTLA-4 are reported to have association with several cancers including HCC, colorectal cancer, and head and neck cancer." (PMID 35525950, 2022). "The top 10 canonical pathways were linked to cellular signaling processes related to immune responses (i.e., antigen presentation, PD-1, PD-L1 cancer immunotherapy, B cell development, IL-4 signaling, Th1 and Th2 activation pathway, and phagosome maturation)." (PMID 36531611, 2022). "In both studies, the antigen presentation pathway and the PD-1, PD-L1 cancer immunotherapy pathway resulted the most significant among B cell development, Th1 and Th2 activation pathway, and IL-4 signaling." (PMID 36531611, 2022). "Among those cytokines, the interleukin (IL)-4/IL-13 cytokine-receptor system has been shown promote cancer cell survival, invasion, and metastasis both directly as well as via interactions with various immunoregulatory cells, such as TAMs and mast cells." (PMID 35409019, 2022). "Th2 cell is a type of T helper cell that can produce IL-4, resulting in activation of several cancer-related pathways." (PMID 35705628, 2022). "IL-4 can promote macrophage and Th cell production, which in turn supports progression of cancers like HCC." (PMID 35525950, 2022). "To explore the effect of TAMs on cancer cell behaviors, we generated M2 macrophages from U937 cells by treatment with IL-4/IL-10 and HCC cells/U937 cells coculture CM, named M2 MφsCyto and TAMsCM, respectively." (PMID 36411463, 2022). "Treatment with naringenin, either alone or combined with CPT, also resulted in a significantly reduced production of IL-4, the most important Th2 cytokine that promotes the proliferation and survival of several cancer cells." (PMID 35606804, 2022). "IL-4 and IL-13 contribute to cancer progression in various cancer types, and several mechanisms have been documented." (PMID 34769439, 2021). "While IL-4, IL-5 and IL-13 have been documented to contribute to cancer growth and metastasis, a dual pro- and anti-tumorigenic role of IL-10 has been reported in recent literature, as reviewed elsewhere." (PMID 34012451, 2021). "The anti-inflammatory cytokines such as IL-4 and IL-10, which were considered protected cytokines in the past, become a double-edged sword in the protection of cancer." (PMID 34803728, 2021). "Th2 cytokines,such as IL-4 and IL-10, are increased in late-stage cancers in comparison to Th1 cytokines that are more prevalent in the early-stage." (PMID 34025655, 2021). "Chimeric proteins composed of IL-13 or IL-4 with PE were invented to target human cancer cells expressing the corresponding receptors." (PMID 33450900, 2021). "Genes in cluster 3 were significantly associated with immune response pathways including antigen presentation, Th1 and Th2 activation, B cell development, neuroinflammation signaling, PD-1 and PD-L1 cancer immunotherapy, and IL-4 signaling pathways." (PMID 34880292, 2021). "It has been reported that interleukin-4 (IL-4) and IL-4Rα (IL-4 receptor) were highly expressed in various human cancer cells following radiation treatment." (PMID 33390846, 2021). "On the other hand, M2 macrophages triggered by IL-4 and IL-13 are often used to facilitate cancer progression." (PMID 35493265, 2021). "This delicate interaction between muscle and cancer cells is accompanied by several processes: an increase in IL-4 and IL-13 secretion, an overexpression of annexin A5 and syncytin 1 and a noticeable fusion of cancer cells." (PMID 33841508, 2021).
cancer (continued). "Considering the cytokines produced in the TME, the role of the interleukin-4 (IL-4)/interleukin-13 (IL-13) cytokine-receptor system has shown significant influence on cancer cell survival, progression, and metastasis." (PMID 33804263, 2021). "Increased production of IL-4 has been confirmed in cancer of the prostate, breast, lung, and kidney cells, as well as many other types of cancer." (PMID 33808304, 2021). "Other studied genes such as IL-4 and Oct4 which were selected by the Laplacian score are also of great importance in cancer development." (PMID 34181334, 2021). "Reactome aggregation analysis (FDR < 0.01) showed that the red target group was mainly associated with four pathways: IL-4 and IL-13 signaling, ESR-mediated signaling, PI3K/AKT signaling in cancer, and signaling by VEGF." (PMID 34394377, 2021). "Elevated levels of IL4, IL13, or their receptors have been associated with poorer patient outcomes such as cancer progression, recurrence, or reduced survival." (PMID 34235145, 2021). "The HMC3 cells were stimulated with a cytokine cocktail known to originate from cancer cells, that was comprised of interleukins IL-4, IL-13, IL-10, growth factors TGFβ1/TGFβ2, and chemokine CCL2." (PMID 34566949, 2021). "The activation of IL4Rα/IL13Rα1 by IL4/IL13 stimulates JAK1/JAK2/JAK3-STAT6-mediated proliferation of cancer cells." (PMID 33419470, 2021). "IL-4 and IL-13 as well as their receptors are expressed in and play important roles for the progression of several different kinds of cancers." (PMID 33450900, 2021). "IL-6 was found to stimulate the cancer-promoting macrophage phenotype change through regulating the level of receptors for IL-4." (PMID 33804263, 2021). "M2 macrophages, which exert an immunosuppressive phenotype by the secretion of anti-inflammatory cytokines (i.e., IL-4, IL-10, and IL-13), were the only pro-cancer immune cells that were higher in high-thermogenesis TNBC." (PMID 34071012, 2021). "Nevertheless, increasing activities of IL-4 and IL-13 in cancers such as lymphoma, breast, lung, colorectal, and oral squamous cell, as well as pancreatic have been found closely associated with tumorigenesis and metastasis." (PMID 33804263, 2021). "The studies on the effect of xanthone 1 on cytokine expression and NO production were not able to explain the dependent increase of the antitumor effect of IL-4-stimulated macrophage supernatants against the cancer cell lines." (PMID 34207168, 2021). "IL-4 is often enriched in the microenvironment of human solid tumors, notably in cancers with high γδ T cell infiltration, such as breast cancer." (PMID 33042132, 2020). "Scratch assay was used to evaluate the effect of exogenous IL-4 and IL-13 (100 ng/mL) on the migratory properties of cancer cells recorded at 0, 24, 48, and 72 h." (PMID 32512917, 2020). "Conversely, Th2 cells demonstrate pro-cancer function via the secretion of interleukin-4 (IL-4), interleukin-6 (IL-6), interleukin-10 (IL-10), and transforming growth factor-β (TGF-β)." (PMID 32370060, 2020). "As well, we identified several proinflammatory cytokines such as IL-1 alpha, IL4, IL6, LIF, TNF which have been implicated in cancer cachexia." (PMID 33334063, 2020). "These mice are selectively deficient for IL-4 only in basophils and are thus suitable to assess the role of basophil-derived IL-4 in different pathophysiological conditions, including cancer." (PMID 33013885, 2020). "The similar results of growth promotion were obtained in this study when cancer cells were treated with IL-4 under nutritional stress conditions." (PMID 32512917, 2020). "Alternatively, stimuli such as IL-4, IL-14, IL-10 can induce macrophages towards an anti-inflammatory and cancer-promoting M2 phenotype." (PMID 33329573, 2020). "IL-4 production by CSCs enhances cancer growth, resistance to therapy and mediate effector T cells suppression." (PMID 32391048, 2020).
cancer (continued). "Despite the complex relationship between cancer and endogenous IL-4, administration of supraphysiologic quantities of this cytokine has been extensively explored for the treatment of several cancers." (PMID 32391013, 2020). "Available literature presents contradicting data concerning effects of IL-4 and IL-13 on cancer cell proliferation and ability to evade pro-apoptotic signals." (PMID 32512917, 2020). "The rs2070874 T>C, located in the 5′-UTR region of the IL-4 gene, is an important SNP in cancer development." (PMID 32744314, 2020). "Malignant tumours break this balance by recruiting macrophages through chemokines like M-CSF and IL-4, leading to a transformation into M2-like polarised TAMs." (PMID 32075091, 2020). "IL-4 is a cytokine that is produced by T lymphocytes, basophiles, and mastocytes, as well as different types of cancer cells." (PMID 33321722, 2020). "The role of IL-4 and IL-13 in leukocyte biology and hematological malignancies is well established and their involvement in activation of cancer-promoting macrophages and myeloid-derived suppressor cells is increasingly being recognized." (PMID 32512917, 2020). "In the secretome of patients with advanced carcinoma, it has been possible to find a positive correlation between the secretion of IL-6, IL-1β, IL-2, and IL-4 and the concentration of MGAs." (PMID 32630302, 2020). "On the front of cancer cells, both H460R and A549R cells showed a significant increase in the mRNA level of Src, IL-4, IL-10 and MIF as compared to their parental counterparts." (PMID 31036057, 2019). "IL-4 is thought to be controversial for cancer therapy because multiple forms of cancer express the IL-4R." (PMID 30842774, 2019). "STAT6 in CD11b+ cells increases IL-4 secretion, which in turn increases M2 myeloid cells and promotes cancer cell proliferation." (PMID 31798581, 2019). "In the tissue, CD4+/IL-4+ and CD20+/IL-10+ cells were positively associated with miR-21 and CD4+/IFN-β, thyroid hormone, and cancer signaling pathways were shared between miR-21, miR-31, miR-23b, miR-146a, miR-1246, and miR-150." (PMID 32082077, 2019). "A significant association between IL-4-590C/T variant and smoking-related cancer in total population was revealed in our meta-analysis results, and IL-4-590C/T variant might have a relatively protective effect on smoking-related cancer (CT vs. TT: P=0.026, OR = 0.900, 95% CI: 0.820–0.987)." (PMID 31871935, 2019). "For instance, cathepsin protease activity is induced by IL-4 in TAMs and promotes cancer growth and invasion." (PMID 31629410, 2019). "Interleukin-4 (IL-4) has several pathophysiologic and therapeutic links to cancers and can promote the function of CAR-T cells." (PMID 29568411, 2018). "The secreted IL-4 bound to its receptor on the cancer cell membrane further induced downstream signaling activation to mediate cancer stemness." (PMID 29615105, 2018). "Production of IL-4 by spleen cells of IL-23R KO mice increased slightly as lesions advanced to cancer, at which point similar levels were produced by spleen cells of the IL-23R KO and wildtype mice." (PMID 29664967, 2018). "Previous studies indicated efficacious treatment against cancer due to the blockade of IL4 where the functional role of IL4 cytokine was demonstrated as an important mechanism that protects the tumorigenic CD133+ cells from apoptosis." (PMID 30326660, 2018). "The most validated cytokines involved in cancer progression are IL-1, IL-4, IL-6, while IL-2 has been the most understood anti-inflammatory cytokines used to boost the host immunity against cancer." (PMID 28927416, 2017). "The expressions of IL-4, IL-10 and IL-13 were significantly decreased in the metformin-treated cancer cells compared to the control cells." (PMID 28157701, 2017). "First IL-4 can exert growth-stimulatory and pro-invasive effects in several cancer cells including the pancreas." (PMID 28350325, 2017).
cancer (continued). "Several studies have revealed a close relationship between IL-4 and cancer cell stemness properties." (PMID 28927416, 2017). "This property of receptor sharing for IL-4 and IL-13 has also been observed in other cancer cell lines." (PMID 28752098, 2017). "The present review summarizes the most known cancer-related cytokines IL-2, IL-1, IL-4 and IL-6 as regulators of carcinogenesis and cancer maintenance or eradication." (PMID 28927416, 2017). "rs2243250 (IL4) and rs5275 (PTGS2) were found to be significantly associated with shorter cancer-specific survival (CSS)." (PMID 28117391, 2017). "Numerous cytokines have been reported to recruit MDSCs in cancer tissues, such as IL-1β, IL-6, IL-4, macrophage colony-stimulating factor, and granulocyte macrophage colony-stimulating factor." (PMID 29326716, 2017). "Cancer cells secrete anti-inflammatory cytokines such as IL-4, IL-10, and TGF-β and induce systemic inflammation and suppress lymphocyte function." (PMID 28938679, 2017). "We found that interleukin-4 (IL-4) and IL-4Rα (IL-4 receptor) are highly expressed in various human cancer cells subsequent to radiation treatment." (PMID 27895317, 2016). "In OSCC tissues, IL-10+ and IL-4+ macrophages were predominantly seen in the cancer nests, and some positive signals were also found in cancerous epithelial tissues." (PMID 28053372, 2016). "We found that IL-4 level is significantly upregulated in tissues of cancer patients and cancer cell lines." (PMID 27895317, 2016). "Edema formation resulting from vascular leakage is an important consequence of allergic inflammation and a most common side effect of IL-4 therapy in human cancer patients." (PMID 27214384, 2016). "In this study, we have identified miR-340 and miR-429 as specific miRNAs for the IL-4 directed gene regulation in cancer cells." (PMID 27895317, 2016). "It is therefore hoped that other types of DCs, that are ideally more potent than GM-CSF and IL-4 derived DCs, will fulfill the promises of DC-based cancer therapies." (PMID 27431276, 2016). "The recruitment and activation of immune cells and the antitumor effects of IL-4, an anti-inflammatory cytokine, are involved in the inhibition of angiogenesis, inflammation, thrombosis, growth, and invasion in some cancers." (PMID 26989335, 2016). "Increased expression of IL-4 and IL-4 receptor (IL-4Rα) has been reported in several cancer cell types, including breast, ovarian, colon, lung, and thyroid cancers." (PMID 27895317, 2016). "The Cancer Genome Atlas (TCGA) dataset shows that the expression of IL-4 mRNA is upregulated in various cancer patients (left)." (PMID 27895317, 2016). "The results showed that papaya extract significantly inhibited growth of cancer cells and down-regulated the expression of pro-inflammatory cytokines IL-2 and IL-4." (PMID 27769229, 2016). "The expression of IL-4Rα mediates the action of IL-4, so we performed the Western blot analysis to investigate the IL-4Rα expression of various cancer cells." (PMID 26993600, 2016). "Here, we report that IR-induced IL-4 signaling is strongly associated with EMT, migratory potential, invasiveness, angiogenesis, stemness maintenance, and metastasis of cancer cells." (PMID 27895317, 2016). "All these results taken together indicate that IL-4 is involved in IR-induced acquisition of tumorigenic properties by human cancer cells." (PMID 27895317, 2016). "IL4 is overexpressed in different types of cancer including breast, ovarian, colon, lung, and thyroid." (PMID 27259269, 2016). "Numerous DC-based immunotherapy trials for treatment of cancer(s) have been carried out with monocyte-derived DCs that were generated in vitro using GM-CSF and IL-4." (PMID 27431276, 2016). "IL-4 has an inhibitory role in angiogenesis, as well as in cancer growth such as multiple monocyte, lung, kidney, liver, and breast cancer cells." (PMID 26993600, 2016).
cancer (continued). "Expression of IL-4 and IL-4Rα proteins was upregulated by IR treatment in various cancer cell lines, including MCF-7, MDA-MB-231, A498, Caki-1, and HEK-293 cells, suggesting that this phenomenon is generalizable." (PMID 27895317, 2016). "IL-4 has an inhibitory role in angiogenesis, as well as in cancer growth, such as multiple monocyte, lung, kidney, liver, breast." (PMID 26993600, 2016). "To confirm the effect of IL-4 on cancer cell phenotype, we used a recombinant IL-4 (0.5 ng/mL) or an anti-IL-4 antibody (10 μg/mL) and examined changes in mesenchymal trait, migration, invasion, angiogenesis, and stemness in A498 cells." (PMID 27895317, 2016). "In various human cancers malignant cells and host infiltrating cells express and secrete a range of Th1, Th2, and Th17 cytokines (IL-1β, IL-2, IL-4, IL-6, IL-10, IL-17, and IFN-γ) and TGF-β." (PMID 27777963, 2016). "M2 type macrophages, one type of inflammatory cells that are differentiated by IL-4 and IL-13 stimulations, are known as major mediators linking cancer and inflammation." (PMID 26790618, 2016). "Mast cells play a key role in the pathogenesis of cardiovascular diseasesand cancers via secreting a variety of cytokines includingTNF-α, IL-3, IL-4, IL-5, IL-6, IL-10, IL-13, IL-14 and IL-16." (PMID 26625310, 2016). "We describe the allelic distributions of four IL1A (rs3783553), IL4 (rs79071878), NFKB1 (rs28362491) and PAR1 (rs11267092) gene polymorphisms, which the literature describes as polymorphisms with a risk of cancer or worse prognosis for cancer." (PMID 26879815, 2016). "We must know the distribution of allelic frequencies of these polymorphisms [IL-1A (rs3783553), IL4 (rs79071878), NFKB1 (rs28362491) and PAR1 (rs11267092)] for association studies on cancer, data for which is limited on Brazilian populations." (PMID 26879815, 2016). "In light of this finding it is important to note that direct stimulation of cancer cells with IL-4 generally results in augmented growth and proliferation." (PMID 26498838, 2015). "Most clinical trials of DC-based cancer immunotherapy have been conducted using the so-called “interleukin (IL)-4 DC” type." (PMID 25951230, 2015). "This was also supported by in vitro co-culture analysis that showed a correlation between cancer cell IL-4 expression and enhanced macrophage survival, fusion and phagocytic behavior." (PMID 27563494, 2015). "In our experiments, morphine prevented MMP-9 increase and arginase-1 induction in both models of activation (treatment with IL-4 and coculture with cancer cells) in RAW264.7 and BMM cells." (PMID 26078009, 2015). "Flow cytometry assessment of these tumors revealed evidence of increased cancer cell phagocytosis by TAMs, and co-culture experiments suggested that cancer cell derived IL-4 promoted macrophage survival and phagocytic activity." (PMID 27563494, 2015). "Clinical trials have shown that systemic administration of IL-4 plus GM-CSF was able to enhance dendritic cell number and their functions in cancer patients." (PMID 27563494, 2015). "In cancer cell lines, variations in the activity of IL4 and its receptor have been shown to modulate cell proliferation and to affect signal transduction pathways." (PMID 26383107, 2015). "For instance, il1b, which promotes early cancer angiogenesis, was significantly upregulated while anti-tumor cytokines, il4, il6, il8, il10, il12, and tnfa, all showed significant downregulation." (PMID 25828472, 2015). "Flow cytometry analysis indicated enhanced cancer cell phagocytosis by TAMs from IL-4 expressing tumors, and co-culture studies showed that IL-4 expressing cancer cells supported the survival and promoted the in vitro phagocytic behavior of macrophages." (PMID 27563494, 2015).